CD36 (CD36 molecule (CD36 blood group))
Diseases named in the same sentence as CD36 in open-access papers (continued):
Sharing a sentence is not in itself a finding about the gene and the disease.
cancer (continued). "While there remains a lot of optimism about VT1021 and humanized CD36 antibodies in the context of cancer therapies, we anticipate that these molecules will also find broad utility in the treatment of other CD36-associated metabolic diseases." (PMID 37371076, 2023). "In recent years, CD36 has quickly emerged as a promising therapeutic target to treat cancer, with broad clinical implications." (PMID 37371076, 2023). "CD36 plays a vital role in modulating cancer development, metastasis, therapy resistance, and prognosis." (PMID 37927468, 2023). "Given its broad expression pattern and eclectic roles in promoting the growth and treatment resistance of many different types of cancer, CD36 is emerging as a promising therapeutic target." (PMID 37371076, 2023). "Metastasis-initiating cells express CD36, and blocking this receptor inhibits metastasis formation in human oral carcinoma and other human cancer types." (PMID 36980201, 2023). "All in all, CD36 inhibition appears to have the potential to confer numerous mechanistically distinct therapeutic benefits to cancer patients." (PMID 37371076, 2023). "In cancer cells, CD36 functions primarily as a FA transporter that mediates the uptake of extracellular FAs to support the metabolic needs of the cell, such as fueling the energetic demands of metastasis." (PMID 37371076, 2023). "In summary, the prospective benefits of CD36-targeted therapy are multifaceted and have the potential to be a paradigm-shifting approach in the battle against cancer." (PMID 37371076, 2023). "In the same direction, a recent study has shown that CD36 blocking leads to cancer progression inhibition by lipid droplet accumulation decrease and intracellular ROS production reduction." (PMID 37760840, 2023). "While a lot has already been discovered about CD36 in other cell types, the role of CD36-mediated cell signaling in cancer cells remains largely uncharacterized and warrants further study." (PMID 37371076, 2023). "NRP1 was closely associated with a variety of genes in pan-cancer studies, such as IGF-1, PDIA3, and CD36." (PMID 37450415, 2023). "An attractive strategy for cancer treatment is represented by the inhibition of CD36 fatty acid transport proteins, which has been shown to induce the antitumoral infiltrating effector T cells accumulation and depletion of Tregs in the TME." (PMID 37760840, 2023). "Together, these studies demonstrate that CD36 has the potential to facilitate the development of resistance for a large number of therapies across cancer types via a number of functionally distinct and context-dependent mechanisms." (PMID 37371076, 2023). "Accumulating evidence strongly suggests that CD36 plays critical roles in many different cancer types." (PMID 37371076, 2023). "Transwell migration and invasion assays showed that when CD36 was knockdown in cancer cells, their migration and invasion abilities were significantly impaired." (PMID 37207149, 2023). "The uptake through fatty acid translocase (FAT), also known as CD36, also contributes to the cellular pool of lipids in various types of cancers." (PMID 37256177, 2023). "Diacylglycerolyltransferase 1 inhibitor A922500 and neutralizing anti CD36 antibodies can prevent the formation of LDs and limit the invasion of cancer cells." (PMID 37305043, 2023). "This prosaposin-derived peptide has since been further developed and is currently being evaluated in clinical trials as VT1021, the only CD36-targeting agent in trials for cancer therapy at this time." (PMID 37371076, 2023). "Increased CD36 expression levels in TAMs is conducive to an immunosuppressive function and cancer progression by enhancing fatty acid absorption and FAO." (PMID 37545500, 2023). "It is though to be important in many types of cancer and is high expression of CD36 is correlated with cancer drug resistance, including irinotecan." (PMID 38304289, 2023).
cancer (continued). "The lipid scavenger receptor cluster of differentiation 36 (CD36) has been shown to have a pro-metastatic function in several cancers." (PMID 36042102, 2023). "Several studies have shown that the inhibition of FASN can lead to the compensatory upregulation of CD36 expression and that inhibiting both pathways is lethal to cancer cells, highlighting the essentiality of FA pool maintenance in cancer." (PMID 37371076, 2023). "Our findings suggest that hypoxia in the peritoneal cavity enhances CD36 expression in GC cells and promotes the migratory and invasive abilities of cancer cells via the intracellular uptake of adipocyte-derived exogenous PA." (PMID 36042102, 2023). "Recently, the role of CD36 has been receiving attention not only in cancer cells but also in immune cells within TME." (PMID 38060103, 2023). "CD36 expression has been shown to exhibit a prognostic value among patients across a wide spectrum of cancers, and pharmacological inhibition has demonstrated efficacy in numerous pre-clinical in vivo models." (PMID 37371076, 2023). "We are only beginning to understand the complex role of CD36 as a mediator of the interaction between cancer cells and stromal cells in the TME." (PMID 37371076, 2023). "The SMC state presented an intermediate expression level of MITF, but also showed strong down-regulation of the cancer cell metabolic signature with features of nutrient-deprivation, such as enhanced expression of the fatty acid translocase CD36." (PMID 36675114, 2023). "The activity of some of those inhibitors has been studied in cancer models, providing further support to the idea that targeting CD36 as a valid strategy for cancer treatment." (PMID 36568966, 2022). "In cancer cells, CD36: 1) increases fatty acid uptake, reprogramming lipid metabolism; 2) favors cancer cell proliferation, and 3) promotes epithelial-mesenchymal transition." (PMID 36568966, 2022). "CD36 expression has been reported in cancer cell lines from different intrinsic subtypes: luminal; basal and HER2-enriched, but further studies are required to analyze its functional role in those subtypes." (PMID 36568966, 2022). "CD36 accounts for free fatty acid and cholesterol uptake and intracellular signaling, playing a critical role in cancer-related antigen presentation, inflammation and angiogenesis." (PMID 35785165, 2022). "CD36+ cancer cells are thought to gain the energy for anchoring and surviving at sites distant from the tumor origin." (PMID 35457118, 2022). "In this manuscript, we reported an extended study on the growth suppression of multiple cancer cell lines with ligands derived from CD36+ fibroblasts or an agonist for one of the ligands, PENK." (PMID 36361532, 2022). "CD36 was found to transport fatty acids into cells and play a vital role in cancer cell growth, metastasis, as well as epithelial-mesenchymal transition." (PMID 35785165, 2022). "One promising strategy is to target CD36 as therapeutic potential of metabolic interventions on the complex modulation of lipid metabolism in both CD36-faciliated cancer metastasis and TAMs immunosuppression." (PMID 36428985, 2022). "A recent pan-cancer study revealed that CD36 expression in tumoral tissue and adjacent normal tissues or in cancer cell lines varied, being increased or decreased in tumors according to cancer type." (PMID 36556492, 2022). "The role of CD36 in T cell metabolism and function has drawn increasing attention in the context of cancer immunotherapy." (PMID 35438721, 2022). "Targeting FA synthesis (FASN), oxidation (CPT1), or uptake (CD36) sensitizes cancer cells to chemotherapy in adult models." (PMID 35764645, 2022). "CD36 has also been reported to contribute to cancer progression and metastatic potential by activating CSCs, EMT, and chemoresistance." (PMID 35892853, 2022). "For example, CD36 expression or the levels of related lipogenic enzymes are different in various types of cancer cells." (PMID 35735113, 2022).
cancer (continued). "Blocking of CD36 almost stops the migration of oral cancer cells in mouse models, and some other cancer cell metastasis can also be impaired." (PMID 36588702, 2022). "Overall, the evidence compiled points that CD36 is a valid target for the development of new anti-cancer therapies." (PMID 36568966, 2022). "Altered CD36 expression is reported in breast and cervical cancers, with many experimental findings strongly suggesting CD36 to be a key player in promoting gynaecological cancer progression via its role as an FA uptake protein." (PMID 35448537, 2022). "A recent study revealed that CD36, a well-known fatty acid translocase, is correlated with the metastatic ability of cancers and is involved in hepatic VLDL secretion." (PMID 35457118, 2022). "CD36 has been widely reported as a prognostic marker in various cancers, including gliomas and breast, prostate, ovary, colon, and liver cancers." (PMID 35790992, 2022). "Previous research proved that OC cell lines co-cultured with human adipocytes have enhanced expression of CD36/SR-B2, which augments fatty acid influx to cancer cells." (PMID 36012230, 2022). "The discovery that the fatty acid transporter CD36 plays indispensable roles for cancer metastasis further highlights the importance of fatty acid metabolism in cancer metastasis." (PMID 35259022, 2022). "In the studies showing a positive relationship between CD36 and malignancy, exogenous FAs were abundantly provided and cancer cells upregulated CD36 expression for FA uptake to promote aggressiveness." (PMID 35448537, 2022). "In summary, anti-CD36 antibodies blocking the FA and the oxLDL transport in vivo models in different types of cancers have an antitumor, antimetastatic effect and decreased the CSC." (PMID 36568966, 2022). "CD36 plays a role in the initiation of cancer and is correlated with poor prognosis in melanoma and breast cancer." (PMID 35634242, 2022). "CD36 has a crucial role in immune suppression in cancer by enhancing T cell dysfunction and cancer progression." (PMID 36132984, 2022). "CD36 is a key molecule in fatty acid transport and is generally expressed in both white and brown adipocytes; the disseminated cancer cells were stained slightly for CD36." (PMID 36434071, 2022). "In AML, CD36 cooperates with soluble signals from the TME to promote cancer progression and resistance to chemotherapy." (PMID 36568966, 2022). "A high expression of FFA receptors, such as CD36, is characteristic of metastasis-initiating cells and portends poor clinical outcomes in many cancer types, including ovarian, prostate, and breast carcinoma and melanoma." (PMID 35252551, 2022). "In recent years, more and more studies have focused on ox-LDL and cancers, and it has been found that the elevated levels of ox-LDL, as well as LOX-1 and CD36, are related to the increased risk of various cancers." (PMID 35251975, 2022). "CD36/SR-B2 is involved in binding and subsequently mediating the influx of long-chain fatty acids, oxidized lipids and phospholipids to cancer cells." (PMID 36012230, 2022). "In order to elucidate the role of CD36 in cancer, a comprehensive study of the structure and function of CD36 is necessary." (PMID 36354702, 2022). "Pharmacological intervention results are consistent with cell surface CD36 being an important promoter of cancer aggressiveness." (PMID 35991116, 2022). "Within tumors, CD36 is expressed by cancer cells but also by microvascular endothelial cells, stromal cells and immune infiltrating cells." (PMID 36568966, 2022). "The co-culture also promotes the activation of the ERK1/2 and STAT3 signaling pathways with a concomitant increment of the population of cancer cells with a stem cell immunophenotype (CD44+/CD36+)." (PMID 36568966, 2022).
cancer (continued). "Its function in lipid-mediated cell reprogramming (EMT) and immune cell activation has led to the testing of CD36 inhibitors in clinical trials in patients with cancer." (PMID 35406772, 2022). "CD36 can promote the synthesis and storage of FA, so inhibiting the production of CD36 or modifying the binding site of CD36 can promote the apoptosis of cancer cells." (PMID 35743814, 2022). "CD36-driven fatty acid metabolism contributes to the growth and metastasis of multiple cancers in a cancer cell-intrinsic manner." (PMID 36184646, 2022). "A recent study indicates that CD36 expression positively correlates with the immune and stromal scores of different types of cancer." (PMID 36361532, 2022). "Since previous studies have implicated CD36’s involvement in the metastatic process and regulation of EMT in cancer, the goal of this study was to evaluate the contribution of CD36 to CRC metastasis." (PMID 35008415, 2022). "The results indicate that, in fact, the influence of CD36 on patient prognosis depends on the type of cancer." (PMID 35159947, 2022). "Such apparently opposing effects of CD36 expression in cancer cells vs. CAFs make it difficult to target CD36 directly for cancer therapy." (PMID 36361532, 2022). "Herein, we review the role of CD36 in cancer progression, its participation in stemness control, as well as the efficacy of reported CD36 inhibitors in cancer cell cultures and animal models." (PMID 36568966, 2022). "Our scRNA-seq profiling together with the mining data showed that CD36 was mainly expressed by monocytes/macrophages while CD47 was broadly expressed particularly by cancer cells." (PMID 35547750, 2022). "Aside from its pro-survival and tumorigenic properties, CD36 has been implied in the promotion of invasion and metastasis of multiple types of cancer." (PMID 35008415, 2022). "In summary, CD36-targeted nano-immunotherapy plays a pivotal role to revolutionize the treatment of cancer." (PMID 36428985, 2022). "This cancer phenotype reversal is largely attributed to the inhibition of CD36-mediated FA uptake as signified by the reduced formation of lipid droplets." (PMID 35448537, 2022). "High CD36 expression has been reported in various cancer types and is correlated with poor prognosis in cancers." (PMID 35163079, 2022). "CD36 expression and associated metabolic exhaustion are common features of intratumoral CD8 T cells across multiple cancer models and types." (PMID 34983949, 2022). "GLUT1, FABPpm, MCT4 and SNAT1 genes were significantly overexpressed in carcinomas compared with controls, while expression of CD36/SR-B2, FATP1, FABP4, GLUT4, ASCT2 and LPL was decreased." (PMID 36012230, 2022). "In summary, the current study found CD36 expression and its prognostic value in multiple cancer types." (PMID 34234847, 2021). "While downregulation of CD36 hasbeen observed in aggressive breast cancers,there is accumulating evidence that cancer progression can be promoted by lipidshijacked from circulation and acquired by cancer cells." (PMID 34603769, 2021). "GLUT4 and CD36, which were previously shown to be cancer oncogenes, were predicted to be downstream targets of DNM3OS." (PMID 34218261, 2021). "The retained binding to collagen is supported by our observations of the anti-CD36 monoclonal antibody (clone FA6–152) failing to inhibit VM formation by the cancer cells." (PMID 34215227, 2021). "In conclusion, oxLDL seems to induce an increased expression of both the Lox-1 and CD36 receptors on HNC cell lines, enhancing their uptake of oxidized LDL and decreasing cancer cell migration via the CD36/β-catenin pathway." (PMID 34063116, 2021). "Intriguingly, immunohistochemical results showed overexpression of CD36 in hepatocytes adjacent to the cancer cells of replacement lesions in chemonaïve CRCLM sections." (PMID 34376784, 2021).
cancer (continued). "Studies across various cancers (gastric, oral squamous cell, prostate and ovarian) have highlighted the role of CD36 in fatty acid import into cancer cells and fatty acid oxidation (FAO) regulation to enhance progression." (PMID 34561446, 2021). "Recently, the functions of CD36 have extended to include lipid metabolism, inflammatory response, and cancer development." (PMID 34561446, 2021). "Similar to CD36, high expression of TGFβ1 was found in the hepatocytes adjacent to cancer cells compared to distal hepatocytes." (PMID 34376784, 2021). "Cancer stem cell- like properties, e.g., migration and proliferation, have also been demonstrated for CD36 overexpressing cells." (PMID 34439279, 2021). "This study indicated that therapies targeting CD36 had great potential to improve the prognosis of cancers by inhibiting metastasis." (PMID 34603046, 2021). "A subpopulation of human carcinoma cells that expressed high levels of the fatty acid transporter CD36 and lipid metabolism genes was identified to possess cancer stemness features and to contribute to a poor prognosis in human cancer patients." (PMID 33987528, 2021). "Other CD36-mediated pathways effecting their function and cancer progression alsocannot be excluded." (PMID 34603769, 2021). "An array of signaling pathways that mediate these patterns have been proposed (see review); however, the precise mechanism by which the reduced uptake of extracellular fatty acids by SR-B2/CD36 influences cancer cell biology remains a mystery." (PMID 33413672, 2021). "CD36, most widely known for its role as a scavenger receptor involved in the uptake of fatty acids, is gaining interest in the field of cancer research." (PMID 34215227, 2021). "Coculture with CD36-KO adipocytes resulted in cancer cells switching toward glycolysis at the expense of mitochondrial oxidation for ATP production." (PMID 34314388, 2021). "To assess the role of CD36 in LCFA uptake in cancer cells, we knocked out the CD36 gene in MCF7 cells by using the CRISPR/Cas9 method and confirmed the loss of expression by Western blotting." (PMID 34314388, 2021). "Although CD36+ cells have the function of lipid uptake, a recent study has shown that their potential for initiating cancer metastasis requires the involvement of CD36-induced FAO activation." (PMID 35003369, 2021). "CD36 was significantly downregulated in CRC tissue, and its expression level was negatively associated with cancer progression." (PMID 34887764, 2021). "CD36 is involved in the activation of cancer stem cells and epithelial-to-mesenchymal transition via TGF-ß." (PMID 34439279, 2021). "Although CD36 expression in cancer cells is low, its expression, induced by adipocyte contact, has been shown to drive cancer progression." (PMID 34314388, 2021). "Among all the significant associations, CD36 expression was negatively correlated with ADORA2A and LAG3 in multiple cancer types, but positively associated with IDO1, IDO2, and KIR3DL1 in multiple cancers." (PMID 34234847, 2021). "Combined, these results suggested that LCFA mobilization from WAT, assisted by adipocytic and endothelial CD36, contributed to cancer aggressiveness." (PMID 34314388, 2021). "Together, these data indicated that CD36 function in adipocytes was more important for intercellular LCFA transport than its function in cancer cells." (PMID 34314388, 2021). "Analysis of cancer cells demonstrated that expression of glycosylated CD36 was very low in the majority of mouse and human cancer cell lines." (PMID 34314388, 2021). "Here, we used mouse and cell culture models to investigate the importance and function of CD36 in adipocytes, the endothelium, and cancer cells for LCFA mobilization from adipocytes and LCFAs’ intercellular transfer." (PMID 34314388, 2021).